LINC01451 (long independently transcribed non-coding RNA 1451)
Synonyms: HCCAT4
Gene: Long non-coding RNA gene on chromosome 9 (136,612,019 to 136,625,416, reverse strand). Ensembl gene ENSG00000279141.
Diseases named in the same sentence as LINC01451 in open-access papers:
LINC01451 is named in the same sentence as 2 diseases in open-access papers, as found by Europe PMC text mining. Sharing a sentence is not in itself a finding about the gene and the disease. The quoted sentences say what the papers report.
bladder cancer (2 papers, 2021 to 2023). "In bladder cancer, the long non-coding RNA LINC01451 was found to bind directly LIN28A and LIN28B and thus provoked the proliferation, invasion, and metastasis of bladder cancer." (PMID 37304235, 2023). "For example, LINC01451 promotes bladder cancer cell proliferation, invasion and EMT by activating the TGF-β/Smad pathway." (PMID 34818994, 2021).
cancer (1 paper, 2023). A tumor composed of atypical neoplastic, often pleomorphic cells that invade other tissues. "Our group previously revealed that aberrant linc01451 in BLCa promotes EMT‐induced cancer progression by activating the TGF‐β/Smad signaling pathway." (PMID 36208024, 2023).